MACC1 (MET transcriptional regulator MACC1)
Diseases named in the same sentence as MACC1 in open-access papers (continued):
Sharing a sentence is not in itself a finding about the gene and the disease.
gastric cancer (continued). "Recently, MACC1 expression has been found in lung cancer, hepatocellular carcinoma, ovarian carcinoma, gastric carcinoma, esophageal cancer, and nasopharygneal carcinoma." (PMID 25003996, 2014). "Our results suggest that MACC1 protein expression is consistent with c-Met expression in gastric cancer specimens, which was up-regulated along with the progression of gastric cancer." (PMID 24325214, 2013). "Our study shows that positive protein expression of c-Met and MACC1 seems to be related to the peritoneal metastasis of gastric cancer, which is consistent with Shirahata, A related conclusions." (PMID 24325214, 2013). "Our study investigated expression of MACC1 and c-Met in gastric cancer, as well as correlated this with clinicopathological parameters." (PMID 24325214, 2013). "Recently, MACC1 expression has been found in lung cancer, hepatocellular carcinoma, ovarian carcinoma, and gastric carcinoma." (PMID 23573286, 2013). "Afterward, MACC1 was quickly found to be involved in tumor formation and migration in a multitude of different solid tumors, including glioblastoma, ovarian carcinoma, gastric cancer, hepatocellular carcinoma, and others." (PMID 37051546, 2023). "Moreover, it was demonstrated that the MACC1 target SPON2 can also induce ERK activation in gastric cancer cells." (PMID 37051546, 2023). "Interestingly, MACC1 also was involved in cytoskeletal organization under metabolic stress in gastric cancer." (PMID 37051546, 2023). "The role of MACC1 in gastric cancer was previously analyzed exclusively in studies with Asian patients, where MACC1 was shown to be a negative prognostic marker and associated with the presence of distant metastasis." (PMID 35406545, 2022). "This also confirms the metastasis-promoting abilities of MACC1 for gastric cancer." (PMID 35406545, 2022). "Additionally, MACC1 overexpression has been reported to induce the growth of several types of cancers, including glioblastoma multiforme and gastric cancer." (PMID 33425885, 2020). "Similarly, MACC1 and HGF levels were correlated with the survival rates of gastric cancer patients, while a different study also demonstrated that MACC1 promotes the progression of epithelial ovarian cancer via the HGF/c-Met signaling pathway." (PMID 33425885, 2020). "MACC1 regulates gastric cancer tumor immunity via the c‐Met/AKT/mTOR pathway." (PMID 31557409, 2019). "Furthermore, we have confirmed the diagnostic and prognostic value of S100A4 transcripts in plasma of patients with CRC or gastric cancer, particularly by combined assessment, together with MACC1 transcripts." (PMID 30927479, 2019). "The upregulation of MACC1 in gastric cancer cells was dependent upon secretion of TGFΒ1 from MSC." (PMID 35582574, 2019). "In addition, MACC1 was found to correlate with vascular invasion and α-fetoprotein levels in hepatocellular carcinoma and with peritoneal dissemination in gastric cancer." (PMID 25009663, 2014). "Immunohistochemical expression of MACC1 in gastric cancer tissues and the statistical analysis of clinical pathological data of patients showed that there was a close relationship between MACC1 which was highly expressed in tumors and lymph metastasis, peritoneal metastasis and hepatic metastasis." (PMID 24325214, 2013). "MACC1 may become a new molecular marker and target for the diagnosis and treatment of gastric cancer proliferation and metastasis." (PMID 24325214, 2013). "MACC1 may be involved in the development of gastric cancer through the HGF/c-Met pathway, or as an independent factor in the gastric process, or through other pathways." (PMID 24325214, 2013). "MACC1 protein was closely related to expression of c-Met in gastric cancer tissues, P = 0.002." (PMID 24325214, 2013). "Thus, the current findings provide evidence that positive expressions of MACC1 and c-Met in gastric cancer are significantly higher in primary tumors which developed lymph node metastasis, compared to those with no metastasis." (PMID 24325214, 2013).
gastric cancer (continued). "MACC1 expression might be an indicator for peritoneal dissemination of gastric cancer, but its specific mechanism is unclear." (PMID 24325214, 2013). "It suggested that MACC1 might play an important role in the progress of liver metastases from gastric carcinoma." (PMID 24325214, 2013). "In conclusion, it was found that expression of MACC1 correlated with c-Met expression and that both of them correlated with the presence of lymph node metastasis, peritoneal metastasis, and hepatic metastasis in gastric carcinoma." (PMID 24325214, 2013). "Moreover, the metastasis-associated in colon cancer 1 (MACC1) protein, which is associated with tumor invasion and metastasis, has been implicated in promoting the Warburg effect via the PI3K/AKT pathway in gastric cancer." (PMID 39990656, 2025). "Furthermore, MACC1 was shown to enhance the migratory, invasive, and angiogenic potential of gastric cancer through the phosphorylation of c-Met and AKT, which stimulates the expression of TWIST1/2, epithelial–mesenchymal transition-associated transcription factors." (PMID 33425885, 2020). "Studies have also found that metastasis associated with colon cancer 1 (MACC1) regulates PDL1 expression and tumor immunity in gastric cancer (GC) cells through the c-Met/AKT/mTOR pathway." (PMID 32863765, 2020). "MACC1 may be a therapeutic target for gastric cancer immunotherapy." (PMID 31557409, 2019). "As the gene encoding the hepatocyte growth factor (HGF) receptor, MET, is a transcriptional target of MACC1, the downstream signaling pathway of HGF-c-MET maybe involved in the mechanism of the“MACC1 regulating the resistant to trastuzumab” in gastric cancer cells." (PMID 27581375, 2016). "Therefore, OR3A4 overexpression may promote growth, invasion, metastasis, and tumorigenesis in gastric cancer in vitro and in vivo by upregulating MACC1 and GNB2L1 expression, and downregulating PDLIM2 and NTN4 expression." (PMID 26863570, 2016). "We previously reported that metastasis-associated in colon cancer-1 (MACC1) contributed to the vasculogenic mimicry in gastric cancer (GC), but it remains unknown whether MACC1 promotes endothelium-dependent angiogenesis of GC and whether TWIST1 is involved in this process." (PMID 27280289, 2016). "MACC1 may be used as a new predictive molecular marker of liver metastasis of gastric cancer, and down-regulation of MACC1 may provide a novel method for blocking the process of liver metastasis from gastric cancer." (PMID 24325214, 2013). "In gastric cancer cells, MACC1 moves through the AKT pathway to regulate PDL1 expression and tumor immunity, promote the Warburg effect, and participate in gastric cancer cell epithelial–mesenchymal transformation." (PMID 36979146, 2023). "The increase in glucose depletion by MACC1 suggests a MACC1-mediated effect on glucose depletion which is present in CRC and gastric cancer." (PMID 33652667, 2021). "Specifically, miR-338-3p inhibited the epithelial-mesenchymal transition in gastric cancer by downregulating ZEB2 and MACC1/Met/Akt signaling." (PMID 28969055, 2017). "MACC1 promoted the Warburg effect via the PI3K/AKT signaling pathway, which enhanced the resistance to trastuzumab in gastric cancer." (PMID 28348518, 2017). "Overexpression of miR-218 significantly downregulated the MACC1 expression and inhibited the MACC1-induced colony formation, migration and invasion in both CRC and gastric cancer cell lines." (PMID 27462788, 2016). "Together, these data indicated that OR3A4 upregulation contributes to metastasis and tumorigenesis in gastric cancer by regulating the activation of PDLIM2, MACC1, NTN4, and GNB2L1." (PMID 26863570, 2016). "MACC1 has been reported as the upstream regulator of c-MET/AKT in hepatocellular cancer, cervical cancer, ovarian cancer, and gastric cancer." (PMID 27581375, 2016).
gastric cancer (continued). "In vitro ectopic overexpression of miR-218 significantly inhibited the luciferase activity of MACC1-3′-UTR and MACC1 protein expression, as well as MACC1-induced migration, invasion and colony formation in CRC and gastric cancer cells." (PMID 27462788, 2016). "In support of this inverse regulation of these two genes, luciferase reporter assay, qRT-PCR and Western blot analysis confirmed the post-transcriptional regulation of MACC1 by miR-218 in both CRC and gastric cancer cell lines." (PMID 27462788, 2016). "When combining S100A4 with circulating transcripts of MACC1, improved survival prediction was seen for newly diagnosed CRC as well as gastric cancer patients." (PMID 27331819, 2016). "Similar to the findings of studies on gastric cancer, MACC1 is significantly independent of MET in BC." (PMID 36979146, 2023). "USP37 and MACC1 were down-regulated after up-regulation of miR-BART1-3p, which may be the key target genes for miR-BART1-3p to regulate the proliferation of gastric cancer cells through exosomes." (PMID 37345178, 2023). "Before this study, the prognostic role of MACC1 in gastric cancer had been analyzed in other studies with a sample size between 98 and 436 patients, confirming the negative prognostic role of MACC1." (PMID 35406545, 2022). "MACC1 can activate hepatocyte growth factor (HGF), and the activated HGF can easily bind to c-MET, which promote the phosphorylation of c-MET, thereby inducing the proliferation and invasion of gastric cancer." (PMID 35874635, 2022). "It was reported that miRNA-338-3p could directly target PREX2a, MACC1, Rab14, RAB23, IRS2, and Sox4 in ovarian cancer, gastric cancer, breast tumor, prostate cancer, non-small cell lung cancer, glioblastoma, and neuroblastoma." (PMID 33817311, 2021). "Subsequent molecular analysis of clinical gastric cancer tissue samples further verified the negative correlation between MACC1 and SPINT1." (PMID 33751856, 2021). "Mechanistically, MACC1 may contribute to cancer progression via the MACC1/hepatocyte growth factor (HGF)/c-Met axis, as has been reported for ovarian cancer, gastric cancer, and HCC." (PMID 33425885, 2020). "MACC1 regulates PDL1 expression and gastric cancer tumor immunity." (PMID 31557409, 2019). "Thus we combined detection of circulating transcripts of S100A4 with those of the MACC1 gene for CRC and gastric cancer patients." (PMID 27331819, 2016). "Global microarray analysis combined with RT-PCR, RNA immunoprecipitation, and RNA pull-down analyses after OR3A4 transfection demonstrated that OR3A4 influenced biologic functions in gastric cancer cells via regulating the activation of PDLIM2, MACC1, NTN4, and GNB2L1." (PMID 26863570, 2016). "We previously reported that metastasis-associated in colon cancer-1 (MACC1) induced the EMT and was associated with a poor prognosis of patients with gastric cancer (GC), but it remains unknown whether MACC1 promotes VM and regulates the TWIST signaling pathway in GC." (PMID 25895023, 2015). "Expressions of MACC1 and c-Met protein in a sample of 98 gastric carcinoma and adjacent nontumorous tissues were detected by immunohistochemistry." (PMID 24325214, 2013). "Rescue experiments with MACC1 overexpression or knock-down of MACC1 and miR-218 clearly revealed that MACC1 as a novel target of miR-218 is at least in part responsible for the significant reduction of migration, invasion and colony formation by miR-218 in CRC and gastric cancer cell lines." (PMID 27462788, 2016). "We speculate that the MACC1 protein may induce the process of EMT in gastric cancer cells through the HGF/c-Met pathway, and consequently influences the peritoneal metastasis of gastric cancer." (PMID 24325214, 2013).
ovarian carcinoma (27 papers, 2011 to 2024). A malignant neoplasm originating from the surface ovarian epithelium. "As a result, the current study investigated the potential association between c-MET and MACC1 in ovarian cancer." (PMID 25009663, 2014). "Compared to normal ovary and benign ovarian tumor, expressions of MACC1 were obviously up-regulated in ovarian cancer tissues, which showed abnormal expression of MACC1 might be associated with ovarian cancer." (PMID 21923915, 2011). "In this study, we detected high levels of MACC1 in ovarian cancer tissues by immunohistochemistry, which showed abnormal expression of MACC1 might be associated with ovarian carcinoma." (PMID 21923915, 2011). "Still, more research is needed to delineate and characterize the function of MACC1 in the context of ovarian cancer tissue." (PMID 39728624, 2024). "In epithelial ovarian cancer cells, it has been shown that MACC1 inhibition increases cisplatin sensitivity in cells that had previously demonstrated cisplatin resistance." (PMID 39728624, 2024). "In epithelial ovarian cancer, it was shown that high MACC1 expression led to reduced OS and progression-free survival in patients." (PMID 39580452, 2024). "In lung cancer and ovarian cancer, overexpressing MACC1 has been demonstrated to overcome chemotherapeutic resistance, and down-regulating MACC1 expression has been found to increase the sensitivity of cisplatin-resistant cancer cells to the drug." (PMID 36979146, 2023). "Our previous data indicated miR-338-3p was downregulated and MACC1 was upregulated in epithelial ovarian cancer, and was related with poor prognosis of ovarian cancer." (PMID 34405027, 2021). "High expression of MACC1 was also proven to be related to poor clinical outcomes in a wide variety of tumors, such as gastric, endometrial, and ovarian carcinomas." (PMID 34577857, 2021). "We report that high MACC1 and S100A4 transcript levels at primary diagnosis of ovarian cancer are associated with advanced disease and predict poor prognosis." (PMID 30927479, 2019). "This is the first study in ovarian cancer to propose circulating MACC1 and S100A4 transcripts as potential liquid biopsy markers." (PMID 30927479, 2019). "In gynecological cancers, studies have shown that compared with normal ovarian tissues and benign cancer tissues, ovarian cancer tissues exhibit higher MACC1 expression levels." (PMID 25009663, 2014). "Down-regulation of MACC1 resulted in significant inhibition of cell proliferation, migration and invasion, meanwhile obvious enhancement of apoptosis in ovary carcinoma cells." (PMID 25003996, 2014). "In the present study, RNAi technology was employed to knock down endogenous MACC1 expression and to analyze the effect of MACC1 on the metastatic behavior of ovarian cancer cells." (PMID 25009663, 2014). "The present study investigated the effect of MACC1 downregulation on the biological characteristics of the ovarian cancer OVCAR3 cell line." (PMID 25009663, 2014). "A tube formation assay using HUVECs was employed to determine the effects of MACC1 on ovarian cancer cell angiogenesis." (PMID 25009663, 2014). "Taken together, these results indicated that MACC1 overexpression promotes the metastasis and invasion of ovarian cancer cells in vitro." (PMID 25009663, 2014). "MACC1 expression in ovarian cancer was significantly higher in primary tumors than in normal tissues." (PMID 24325214, 2013). "MACC1 was reported to be elevated in various cancer tissues, including ovarian cancer, hepatocellular carcinoma, non-small cell lung cancer, and oral squamous cell carcinoma." (PMID 24325214, 2013). "After inhibition of MACC1 by RNAi in ovarian carcinoma OVCAR-3 cells, we observed that level of Met protein was down-regulated significantly, as well as expressions of p-MEK1/2 and p-ERK1/2 protein, but expression of p-Akt was uninfluenced." (PMID 21923915, 2011).
ovarian carcinoma (continued). "The positive rates of MACC1 in normal ovary, benign ovarian tumor and ovarian cancer tissues were detected by immunohistochemistry." (PMID 21923915, 2011). "Furthermore, a study in ovarian cancer demonstrated lower cell–matrix adhesion to matrigel after MACC1 silencing in a 2-h time frame covering the onset of cell attachment." (PMID 37051546, 2023). "In epithelial ovarian cancer tissues, researchers showed that miR-338-3p reduced and was negatively associated with the MET transcriptional regulator metastasis-associated in colon cancer protein 1 (MACC1)." (PMID 37854681, 2023). "In conclusion, the current study reported that MACC1 downregulation may effectively suppress the malignant biological behavior of ovarian cancer and confirmed that c-MET is a target of MACC1." (PMID 25009663, 2014). "All the results indicated that MACC1 is important for the invasion and migration of ovarian cancer." (PMID 25009663, 2014). "Furthermore, a luciferase reporter assay confirmed that c-MET is a target of MACC1 in ovarian cancer cells." (PMID 25009663, 2014). "In summary, our data showed that MACC1 might implicate in growth and metastasis of ovarian carcinoma." (PMID 21923915, 2011). "RNA interference (RNAi) against MACC1 could serve as a promising intervention strategy for gene therapy of ovarian carcinoma, and the antitumor effects of MACC1 knockdown might involve in the inhibition of HGF/Met and MEK/ERK pathways." (PMID 21923915, 2011). "In ovarian carcinoma cells, the antitumor effects of MACC1 RNAi might involve in the inhibition of HGF/Met and MEK/ERK pathways." (PMID 21923915, 2011). "In present study, expressions of MACC1 were detected in different ovarian tissues by immunohistochemistry, effects of MACC1 inhibition on OVCAR-3 cells were observed by RNA interference, and the possible antitumor mechanisms of MACC1 knockdown in ovarian carcinoma cells were discussed." (PMID 21923915, 2011). "As a key regulator of HGF/Met signaling, RNA interference against MACC1 could serve as a promising intervention strategy for gene therapy of ovarian carcinoma." (PMID 21923915, 2011). "Overexpressions of MACC1 were detected in ovarian cancer tissues." (PMID 21923915, 2011). "Thus, we designed and synthesized three specific shRNAs against MACC1 gene to investigate the effects of MACC1 inhibition on ovarian carcinoma OVCAR-3 cells in present study." (PMID 21923915, 2011). "Results of invasion assay indicated invasive potential of ovarian carcinoma cells could be retarded by MACC1 RNAi." (PMID 21923915, 2011). "MACC1 may be important in regulating the tumorigenesis and development of ovarian cancer." (PMID 25009663, 2014). "Inhibition of the function of MACC1 may represent a new strategy for treating ovarian cancer." (PMID 25009663, 2014). "In addition, it is indicated that MACC1 inhibition may be a novel pharmaceutical target for inhibiting ovarian cancer metastasis." (PMID 25009663, 2014). "Finally, a luciferase reporter assay and western blot analysis were used to confirm whether MACC1 functions as a metastatic promoter in ovarian cancer by targeting c-MET." (PMID 25009663, 2014). "Therefore, we presumed that inhibition of MACC1 by RNAi might suppress the malignant behavior of ovarian carcinoma cells via HGF/Met and MEK/ERK pathways, at least in part." (PMID 21923915, 2011). "However, the mechanism of MACC1 implicates in ovarian cancer is still unclear." (PMID 21923915, 2011). "For instance, MACC1 has been found, together with ALDH1, as a prognostic biomarker for non-small cell lung-, hepatocellular- and also ovarian cancer." (PMID 39580452, 2024). "The capacity of MACC1 to upregulate c-MET expression transcriptionally has been shown in CRC, ovarian cancer (OC), pancreatic cancer (PDAC) and osteosarcoma." (PMID 39580452, 2024).